SPACA4 (sperm acrosome associated 4)
Description:
Sperm surface membrane protein that is essential for effective sperm-zona pellucida binding and penetration during fertilization.
Synonyms: SAMP14
Tractability: Antibody: UniProt places it where antibodies can reach, with high confidence; its Gene Ontology location is reachable by antibodies, with high confidence; UniProt predicts a signal peptide or a membrane-spanning region.
Gene: Protein-coding gene on chromosome 19 (48,606,742 to 48,607,714, forward strand). Ensembl gene ENSG00000177202.
Subcellular location: Cell membrane; Cytoplasmic vesicle, secretory vesicle, acrosome; Cytoplasmic vesicle, secretory vesicle, acrosome inner membrane; Cytoplasmic vesicle, secretory vesicle, acrosome outer membrane
Subcellular location (Human Protein Atlas): Acrosome
Pathways (Reactome):
Metabolism of proteins: Post-translational modification: synthesis of GPI-anchored proteins
Gene Ontology:
Biological process: binding of sperm to zona pellucida; fertilization; sperm-egg recognition
Cellular component: acrosomal vesicle; inner acrosomal membrane; outer acrosomal membrane; plasma membrane; extracellular region; membrane
Genetic constraint (gnomAD): Loss-of-function variants: 0 observed, 0.0749 expected, observed/expected ratio (o/e) 0, 90% interval 0 to 1.89. That is too few expected variants to judge how well the gene tolerates losing a copy. Missense variants: 130 observed, 164.46 expected, observed/expected ratio (o/e) 0.79, 90% interval 0.69 to 0.91. Synonymous variants: 63 observed, 72.16 expected, observed/expected ratio (o/e) 0.87, 90% interval 0.71 to 1.08.
Homologues: Orthologues: chimpanzee SPACA4 (100% identical), macaque SPACA4 (90% identical), pig SPACA4 (74% identical), dog SPACA4 (68% identical), mouse Spaca4 (66% identical), rat Spaca4 (64% identical), rabbit SPACA4 (62% identical), zebrafish lye (27% identical).
Diseases named in the same sentence as SPACA4 in open-access papers:
SPACA4 is named in the same sentence as 3 diseases in open-access papers, as found by Europe PMC text mining. Sharing a sentence is not in itself a finding about the gene and the disease. The quoted sentences say what the papers report.
Infertility (1 paper, 2021). "Even though ADAM3 processing was slightly reduced in Spaca4 mutant sperm compared to wild-type sperm, this decrease cannot account for the severe fertilization defect in Spaca4 mutants given that much less of processed ADAM3 is required to rescue infertility mutants." (PMID 34556579, 2021).
tumor (1 paper, 2022). "This study determined that CCR4, TMCO1, and SPACA4 may be potential antigens for HNSCC mRNA tumor vaccine development, and patients with immune subtype C3 might benefit most from mRNA vaccination." (PMID 36671475, 2022). "In this study, we identified three tumor antigens, CCR4, TMCO1, and SPACA4, related to the prognosis and antigen-presenting cell infiltration of HNSCC." (PMID 36671475, 2022). "Three tumor antigens (CCR4, TMCO1, and SPACA4) related to APCs infiltration and prognosis in HNSCC were identified, and it is expected that these genes might become candidate antigens for an mRNA vaccine." (PMID 36671475, 2022). "Furthermore, CCR4 was significantly correlated with tumor infiltration of B cells, CD8+ T cells, CD4+ T cells, and macrophages, while TMCO1 was significantly correlated with CD8+ T cells, and SPACA4 was significantly correlated with B cells, CD8+ T cells and Neutrophils." (PMID 36671475, 2022).
SPACA4 also shares sentences with these, for which no sentence is quoted: Azoospermia (1 paper).